RNU5F-6P (RNA, U5F small nuclear 6, pseudogene)
Gene: Small nuclear RNA gene on chromosome 1 (164,351,273 to 164,351,388, forward strand). Ensembl gene ENSG00000199849.
Homologues: Orthologues: chimpanzee U5 (99% identical), macaque U5 (95% identical). Paralogues in human: RNU5F-7P (78% identical), RNU5E-7P (75% identical), RNU5E-4P (74% identical), RNU5F-3P (73% identical), RNU5F-8P (71% identical), RNU5A-4P (70% identical), RNU5A-8P (70% identical), RNU5E-10P (69% identical), RNU5E-8P (69% identical), RNU5A-7P (67% identical), RNU5B-4P (67% identical), RNU5A-6P (66% identical), and 13 more.